BRCA2 (BRCA2 DNA repair associated)
Diseases named in the same sentence as BRCA2 in open-access papers (continued):
Sharing a sentence is not in itself a finding about the gene and the disease.
tumor (continued). "PARP inhibitors target DNA damage repair pathways leading to synthetic lethality of tumor cells with HRR deficiency, e.g., due to variants in genes such as ATM or BRCA2." (PMID 41546701, 2026). "Dysfunction of homologous recombination genes, such as BRCA1 and BRCA2, contributes to genomic instability and the development of more aggressive tumor clones." (PMID 41899427, 2026). "Talazoparib has shown anti‐tumour activity in patients with advanced breast cancer and in those carrying germline BRCA1 and BRCA2 (BRCA1/2) mutations." (PMID 41537447, 2026). "BRCA1 and BRCA2 are key tumor suppressors, and they are essential for homologous recombination repair (HRR) where BRCA1 promotes DNA end processing and BRCA2 assists RAD51 loading for error-free repair of double-strand breaks." (PMID 41373752, 2025). "We observed the upregulation of genes associated with positive anti-tumor activity, including NR3C1, BRCA1, BRCA2 and SFN." (PMID 40043049, 2025). "The BRCA1 and BRCA2 genes are tumor suppressors involved in DNA repair through homologous recombination, essential for maintaining chromosome integrity as part of the ATM-mediated DNA repair pathway." (PMID 41077566, 2025). "The patient with germline BRCA2 and FANCE pathogenic variants had a loss of expression of both BRCA2 and FANCE in the tumor, suggesting loss of BRCA2 and FANCE function." (PMID 40072012, 2025). "The reasons for this differential effect of hDPP4 on tumour growth depending on BRCA2 status need to be further elucidated." (PMID 40579444, 2025). "The tumour suppressor BRCA2 is a main player in the HR, by chaperoning multiple copies of the recombinase Rad51 that form stable filaments on the exposed ssDNA." (PMID 40293537, 2025). "RNA sequencing suggested a complete loss of expression of HR genes BRCA2 and FANCE in the tumor of a second patient." (PMID 40072012, 2025). "BRCA2 is a tumor suppressor gene and codes for proteins involved in transcription, DNA repair of double-stranded breaks, and recombination." (PMID 39838298, 2025). "Patients with poorer clinical outcomes were more likely to have mutations in BRCA2, ATM, and CDK12, as well as high tumor mutation burden (TMB) and microsatellite instability (MSI)." (PMID 40805284, 2025). "To address the challenges of CNV detection in such samples, we applied ddPCR to analyze BRCA1 exon 22 and BRCA2 exon 27 using DNA derived from both blood and frozen tumor samples." (PMID 40725150, 2025). "This approach bypasses Knudson’s “double whammy” requirement for tumor initiation in the presence of partially preserved BRCA2 function." (PMID 40191206, 2025). "After PARPi treatment for 6 days, the tumor organoids from the xenograft models of the BRCA2 hypermethylated patient showed a decline in tumor cell nuclei, in contrast to the organoids with BRCA wildtype, but similar to the BRCA1 mutated organoids." (PMID 39392573, 2025). "RAD51 and BRCA2, in particular, show promise for predicting tumor aggressiveness and patient outcomes, as well as response to therapy." (PMID 40869030, 2025). "BRCA1/BRCA2 reversion mutations, detected in 20–40% of resistant HGSOC cases via circulating tumor DNA (ctDNA), restore HR function, negating PARPi sensitivity." (PMID 40864792, 2025).
tumor (continued). "We identified methylglyoxal (MGO)-mediated BRCA2 dysfunction as a driver of immune escape, a role for sphingolipid signaling in tumor proliferation and a role for kynurenine metabolism in CD8+ T cell suppression." (PMID 40191206, 2025). "Comprehensive genomic profiling revealed a BRCA2 mutation, homologous recombination deficiency (HRD), microsatellite instability-high (MSI-H), and a very high tumor mutational burden (TMB)." (PMID 41149460, 2025). "For the BRCA1 and BRCA2 tumor suppressor genes, a 20% wild-type expression of the full-length transcript has been designated as sufficient to prevent tumorigenesis by current VCEP specifications." (PMID 39780207, 2025). "This case indeed also showed a BRCA2 methylation in the corresponding primary tumor, which suggests that this alteration is generally preserved during PDX generation." (PMID 39392573, 2025). "BRCA1 and BRCA2 carriers were characterized by distinct patient, tumor, and treatment characteristics and a different pattern and risk of DFS events over time." (PMID 39993249, 2025). "BCCIP (BRCA2‐and cdkn1a‐interacting protein) serves as a critical cofactor for BRCA2 in tumor suppression." (PMID 39932052, 2025). "Recent studies suggest that BRCA1 and BRCA2 expression patterns vary with tumor grade, potentially reflecting their roles in tumor progression." (PMID 40224184, 2025). "For example, DPP9 activity is important for fine-tuning the levels of BRCA2 a prominent tumour suppressor in breast cancer and thus for ensuring correct repair of DNA DSBs by homologous recombination." (PMID 40293537, 2025). "BRCA2 is a tumor suppressor gene involved in DNA replication and, specifically, homologous recombination DNA repair." (PMID 41471728, 2025). "For one of these xenografts, the primary tumor was available, and harbored an identical BRCA2 methylation." (PMID 39392573, 2025). "Removing STING-mediated chemokine induction from the equation by treating Brca2 knockout tumours unresponsive to STING activation resulted in survival benefits that recapitulated the dose-dependent dynamic of cell cytotoxicity by synthetic lethality." (PMID 40579444, 2025). "In our HGSOC patient cohort, high hDPP4 expression correlated significantly with bad prognosis, and this was recapitulated functionally in our murine Brca2 wild-type tumour model." (PMID 40579444, 2025). "Key vulnerabilities, such as BRCA1/BRCA2 mutations, have been exploited with PARP inhibitors, leveraging synthetic lethality to selectively kill tumor cells and improving patients’ survival." (PMID 40422251, 2025). "In vivo, V66-exatecan significantly inhibited tumor growth and extended survival in both TNBC and BRCA-mutant CNS tumors, including complete regressions and prolonged median survival in BRCA2-deficient models." (PMID 41077566, 2025). "Impaired HR through mutations in BRCA1, BRCA2, PALB2, or potentially other mechanisms, can increase the rate of point mutations and random insertions and deletions, promoting tumor neoantigen formation and presentation, and cytotoxic T-cell infiltration." (PMID 40426860, 2025).
tumor (continued). "BRCA1 and BRCA2 are well-known tumor suppressors involved in DNA repair, cell cycle regulation, and maintaining genomic stability, particularly under stress conditions like replication, meiosis, or mitosis." (PMID 41373491, 2025). "Paradoxically, BRCA2-positive tumors were more often low grade and intestinal-type, indicating heterogeneity in BRCA2’s prognostic implications depending on tumor subtype." (PMID 40869030, 2025). "BRCA1 and BRCA2 are tumour suppressor genes responsible for homologous recombination repair of DNA lesions, particularly double-stranded DNA breaks." (PMID 40447784, 2025). "Similar results were observed in BRCA2 mutant tumor lines CAPAN1 and PEO1, which showed increased U-ssDNA and pRPA32 co-staining compared to their isogenic BRCA2-revertant counterparts C2-12 and PEOC4, respectively." (PMID 41162355, 2025). "Case 6, which had the highest number of SNVs, had missense mutations in ATM, POLE and BRCA2, as well as known pathogenic mutations from ClinVar in MSH6, RAD50, APC and NF1, likely explaining the high mutational load in this tumor." (PMID 40670673, 2025). "BRCA2 is a critical tumor suppressor involved in maintaining genomic integrity, notably through homologous recombination (HR) and the protection of stalled replication forks." (PMID 41354653, 2025). "Altogether, this demonstrates the potential of our combinational therapy PADtal and its therapeutic advantage over PADola in suppressing BRCA2 and PALB2‐deficient tumor growth in vivo." (PMID 40823818, 2025). "Inactivation of both BRCA1 and BRCA2 is associated with homologous recombination deficiency (HRD) and, consequently, tumor sensitivity to PARP inhibitors, platinum compounds, and other drugs capable of inducing DNA double-strand breaks." (PMID 40547808, 2025). "Anti-hormonal treatments were more frequently prescribed to BRCA2 and WT carriers, aligning with their hormone receptor-positive tumor subtypes." (PMID 40422528, 2025). "In a patient-derived xenograft humanized germline BRCA2-deficent model with an acquired secondary resistance mutation and a TMB of 12.2 mut/Mb, an anti-PD1 monoclonal antibody significantly slowed tumor growth and promoted tumor T-cell infiltration." (PMID 40426860, 2025). "Since the wild-type BRCA allele is typically lost during tumor development, BRCA1 and BRCA2 are classified as classic tumor suppressor genes." (PMID 41373813, 2025). "As a tumor suppressor, BRCA2 plays a vital role in DNA damage response (DDR), ensuring genomic stability." (PMID 39925800, 2025). "AH-cfDNA revealed additional somatic copy-number alterations, including amplifications (i.e., MDM4 and ALK) and deletions (i.e., BRCA2), indicating progressive clonal tumor evolution." (PMID 41465072, 2025). "The patient with germline BRCA2 and FANCE pathogenic variants had RNA sequencing data that indicated the homozygous loss of BRCA2 and FANCE in the tumor." (PMID 40072012, 2025). "Significant differences in the prevalence of potentially targetable genomic alterations (ATM, BRAF, BRCA2, ERBB2, IDH1, PIK3CA, and PTEN) were observed in MTAP-loss tumors and varied according to tumor type." (PMID 38330461, 2024). "Of 52 tumor samples from the population evaluable by FoundationOne®CDx, 39 (75.0%) and 13 (25.0%) patients exhibited BRCA1 and BRCA2 mutations, respectively; 1 (1.9%) patient exhibited mutations in both genes; and 1 (1.9%) patient had mutations in neither." (PMID 38869771, 2024). "ID8p53–/– Brca2–/–-Egfl6 tumor-bearing mice treated with a-Egfl6 + a-PD-L1 showed a significantly prolonged survival (median survival = 57) compared with IgG isotype control (median survival = 48) (P value 0.0011)." (PMID 39312740, 2024).
tumor (continued). "Several tumors harboring genomic alterations with FDA-approved indications in other tumor types were found including pathogenic PIK3CA, EGFR Exon 19/20 insertions, KRAS G12C (N = 1), FGFR fusions (N = 1), BRAF V600E mutations (N = 4), and BRCA2 (N = 1)." (PMID 39191445, 2024). "This suggests that low RFWD3 expression can influence tumour genotype in a similar way to mutation of FA genes including BRCA1 and BRCA2." (PMID 38711848, 2024). "Germline BRCA1 and BRCA2 alterations increase the probability to develop BC and other tumor types, including ovarian, pancreatic, prostate, colorectal cancer and melanoma." (PMID 39062721, 2024). "BRCA2 is instrumental in the DNA damage response (DDR) pathway, and its mutation can lead to abrogation of DDR, thereby driving genomic instability and tumor heterogeneity." (PMID 38463396, 2024). "Tumour suppressor genes were under episodic positive selection in most taxa, although this pattern was mostly driven by selection in Casp8 and BRCA2." (PMID 38773187, 2024). "PALB2 is a tumor suppressor gene with a role in the homologous recombination repair pathway, through interaction with both BRCA1 DNA repair associated (BRCA1) and BRCA2 DNA repair associated (BRCA2)." (PMID 38792412, 2024). "We depleted CD8+ T cells in ID8p53–/– Brca2–/–-Egfl6 tumor-bearing mice receiving a-Egfl6 combined with a-PD-L1." (PMID 39312740, 2024). "In this case, it is interesting to note the behavior of the BRCA2 gene in an oncogene-addicted tumor." (PMID 39363506, 2024). "Consistent with that and a recent study, depletion of CD8+ T cells did not affect the survival rate of a-Egfl6 + a-PD-L1–treated ID8p53–/– Brca2–/– tumor bearing mice." (PMID 39312740, 2024). "We observed upregulation of both ADAR1 and BRCA2 in chemo‐resistant tumours compared to chemo‐sensitive tumours." (PMID 38773866, 2024). "Our analysis revealed that the upregulation of the SKP2 E3 ligase leads to excessive degradation of BRCA2, potentially promoting tumor cell proliferation and metastasis." (PMID 39062881, 2024). "The main tumor susceptibility genes in CBC3T-1 cells included BARD1, KDR, FAT1, HNF1A, BRCA2, FANCA, and BRCA1." (PMID 37966669, 2024). "BRCA1 and BRCA2 are tumour suppressor genes responsible for repairing double-strand DNA breaks via the homologous recombination repair (HRR) pathway." (PMID 39682099, 2024). "In total, 13 of 97 patients (13%) carried a germline (likely) pathogenic variant in a well-known tumor predisposition gene: APC (n = 1), BRCA2 (n = 2), CHEK2 (n = 4), DICER1 (n = 4), HOXB13 (n = 1), and MITF (n = 1)." (PMID 38415346, 2024). "The loss of tumor suppressors BRCA1 and BRCA2, which are involved in repairing double-strand breaks, can contribute to an abnormal accumulation of R-loops and cytosolic DNA, resulting in a heightened inflammatory response." (PMID 38473997, 2024). "The dysregulated pathway as a result of the BRCA2 mutation resulted in genomic instability, which allowed tumor progression and proliferation via the NOTCH pathway, as seen in the patient with a BRCA2 mutation alongside an aberrant NOTCH2." (PMID 39199639, 2024). "The tumor suppressor genes BRCA1 and BRCA2 are involved in essential cellular functions necessary for cell replication and DNA synthesis, playing a crucial role in DNA repair and tumor suppression." (PMID 39575418, 2024).
tumor (continued). "Nonetheless, some studies suggest that all five structural domains of BRCA2 are crucial for its tumor suppressor function." (PMID 38773604, 2024). "Following this validation exercise, we were able to show a trend towards omental CRS3 in tumours harbouring a germline BRCA2 PV compared to tumours with germline BRCA1/2 wild type." (PMID 39550490, 2024). "The perpetuation of a hypoxic tumour microenvironment by LSD-1 also contributes to the downregulation of BRCA2." (PMID 39682099, 2024). "BRCA1- and BRCA2-altered tumours have shown enhanced immunosurveillance in several preclinical studies, but a correlation between ICB treatment and patient outcome was not evident." (PMID 39271762, 2024). "As CHORD provides subtype-level resolution for HRD, we also mapped CHORD predictions to tumor types to see how the distribution of BRCA1-type HRD compared with that of BRCA2-type HRD." (PMID 39485057, 2024). "We observed significantly slower tumor growth kinetics in ID8Trp53−/−;Brca2−/−-bearing mice compared with ID8Trp53−/−- and ID8Trp53−/−;Brca1−/−-bearing mice." (PMID 39028933, 2024). "Analysis of large‐scale genomic alterations, loss of heterozygosity and tumour mutation burden identified six cases of high genomic instability (including four with pathogenic BRCA1 and BRCA2 mutations)." (PMID 39115191, 2024). "In total, 13 patients (13%) carried a P/LP variant in a known autosomal dominant tumor predisposition gene: APC (n = 1), BRCA2 (n = 2), CHEK2 (n = 4), DICER1 (n = 4), HOXB13 (n = 1), and MITF (n = 1)." (PMID 38415346, 2024). "PARPi significantly alters the therapeutic landscape of tumours with genetic defects, such as BRCA1 and BRCA2 mutations, which are primarily involved in the homologous repair of DNA damage." (PMID 39690136, 2024). "IHC staining revealed a marked decrease in the expression levels of ADAR1, BRCA2, and Ki67 in the tumours of the combination treatment group, suggesting that targeting ADAR1 alongside cisplatin treatment can significantly impair cell proliferation." (PMID 38773866, 2024). "Analysis of BRCA2 expression in TCGA and GEO datasets revealed its upregulation in iCCA tumours compared to non‐tumoural tissues." (PMID 38773866, 2024). "Secondly, it will examine the clinical implications of the interactions between BRCA1, and to a lesser extent BRCA2 PVs, the tumour microenvironment, and epigenetic regulation in terms of prognosis and treatment for hereditary breast cancer." (PMID 39682099, 2024). "Patients with loss-of-function mutations in BRCA1 or BRCA2 can present with a more aggressive BC phenotype, including triple-negative BC (TNBC), higher tumour grade, and higher oncotype risk of recurrence score." (PMID 39215191, 2024). "In physiological conditions, BRCA2 is involved in the maintenance of genome stability, acts as a tumor suppressor, and is also involved in DSB repair." (PMID 39683594, 2024). "Termed tumor suppressor genes, BRCA1 and BRCA2, when harboring specific deleterious variants or mutations, confer a predisposition to carcinogenesis." (PMID 38809921, 2024). "To test this, we analyzed genomes from a diversity of tumor types with driver mutations in either ATM, MEN1, SETD2, BRCA1, BRCA2 and ATRX." (PMID 38909016, 2024). "Using syngeneic 2F8c, ID8, and ID8p53–/– Brca2–/– OvCa mouse models and human OvCa tissue samples, we found that tumor Egfl6 induces the accumulation of intra-tumoral MDSCs and TAMs." (PMID 39312740, 2024). "BRCA2 mutation(c4415-4418del, pathogenic) of patient PGT-M9 was identified through a tumor genetic screening." (PMID 38800375, 2024). "A positive correlation between ADAR1 and BRCA2 expression was observed in both iCCA tumours and non‐tumoural tissues from TCGA, which was corroborated in our iCCA cohort via IHC staining (n = 30)." (PMID 38773866, 2024). "Studies have shown that BRCA1 and BRCA2 help repair the DSBs, initiate HR, and maintain genomic integrity, providing tumor-suppressing effects." (PMID 37509303, 2023).